IL22 (interleukin 22)
Diseases named in the same sentence as IL22 in open-access papers (continued):
Sharing a sentence is not in itself a finding about the gene and the disease.
psoriasis (continued). "In another study, significant differences in IL-17 and IL-22 expression were observed in pediatric psoriasis patients, relative to those in healthy pediatric controls and adult psoriasis patients." (PMID 34440145, 2021). "The interleukins IL-17 and IL-22 produced by Th1/Th17 lymphocytes stimulate IL-8 secretion by keratinocytes, and this represents a key event in the psoriasis pathogenesis." (PMID 34035862, 2021). "Th17 cells, which are stimulated by IL-23, play a central role in psoriasis development through IL-17A and IL-22 production." (PMID 33483537, 2021). "In skin, ILC3s are associated with the pathogenesis of psoriasis through IL23 stimulated IL17 and IL22 production." (PMID 34162906, 2021). "Th17 lymphocytes differentiate under the influence of IL-23, IL-1β, TGF-β and IL-6, secrete IL-17A, IL-17F, TNF-α, IL-21, IL-22, and IL-26, and they play a crucial role in the maintenance of psoriasis chronic inflammation." (PMID 34769005, 2021). "When keratinocytes are stimulated by TNF-α, IFN-γ, IL-22 and IL-17A, they can express the inflammatory marker proteins related to psoriasis, such as chemokines and proinflammatory cytokines." (PMID 34456715, 2021). "The pro-inflammatory cytokines, such as IL-6, TNF-α, IL-1β, IL-22, and IL-17A, have been reported to be up-regulated in psoriatic lesioned tissue and serum, and these cytokines likely drive the psoriasis pathogenesis." (PMID 33323018, 2021). "In psoriasis, an increased proportions of ILC3s were observed in lesional skin and peripheral blood, and IL-22 is regarded as a key driver of epidermal thickening." (PMID 34162906, 2021). "Increased levels of TNF-α, IL-17 and IL-22 are frequently observed in chronic inflammatory skin diseases, including psoriasis, and IL-17 and IL-22 in particular are reported to have a synergistic relationship during inflammatory responses." (PMID 33919521, 2021). "IL-22 has a role in the joint and cardiometabolic involvement of psoriasis, but is essentially dependent on the IL-23/IL-17 axis, since it has a primarily cooperative action with IL-17." (PMID 34829740, 2021). "IL-23 is considered to be a key cytokine in psoriasis that promotes the proliferation of skin-resident T helper cells (especially Th17 and Th22) and the release of IL-17A and IL-22." (PMID 33801280, 2021). "In the IL-23/Th17 axis, IL-23 induces the differentiation of Th17 cells and then promotes the secretion of IL-22 and IL-17, which eventually leads to the aggravation of psoriasis." (PMID 34207960, 2021). "The levels of Th22 cells and plasma IL-22 in patients with psoriasis are increased and positively correlated with the severity of the disease." (PMID 34295334, 2021). "For example, in psoriasis, IL-22 promotes proliferation of keratinocytes, preventing proper differentiation as the cells more rapidly progress through the dermis to the epidermis." (PMID 34868019, 2021). "IL-36 signaling in keratinocytes is crucial for Aldara-induced psoriasis-like dermatitis by controlling IL-23/IL-17A/IL-22 production and neutrophil recruitment at the third day of treatment." (PMID 32345660, 2020). "In line with mRNA expression, the protein expression level of IL-22 was higher in lesions from psoriasis patients than that in HC by ELISA detection (P < 0.01), and IL-22R1 was increased significantly (P < 0.05) by Western blotting detection." (PMID 32632545, 2020). "IL-22 has also been reported as an important cytokine of the IL-17/IL-23 axis of psoriasis, and elevated levels of IL-22 have been shown in the skin and serum of patients, produced by Th22, γδ T-cells, NK cells, and mast cells." (PMID 32392785, 2020). "For example, intrinsic AD in contrast to extrinsic AD showed upregulation of psoriasis-typical genes (e.g., IL22, IL36G, CCL19, and CCL22) complicating discrimination of intrinsic AD and psoriasis." (PMID 31973112, 2020). "The IL-17 and IL-22 cytokines have been considered as hallmarks of the inflammatory phenotype in patients with psoriasis." (PMID 32392785, 2020).
psoriasis (continued). "The proportion of NCR+ ILC3s to total ILC3s is increased in the peripheral blood of psoriasis patients, and NCR+ ILC3s from psoriasis patients are able to produce IL-22." (PMID 32917058, 2020). "In this study, we have explored the relation between IL-22 levels and the severity of psoriasis, and the role of IL-22 in mediating keratinocytes apoptosis in keratinocytes." (PMID 32632545, 2020). "IHC staining showed that psoriasis‐related cytokines IL‐17 and IL‐22 were increased in IMQ and IMQ + Vehicle groups compared to those in control group while ozone therapy decreases their expression." (PMID 32168425, 2020). "IL-22 is known to mediate inflammation in psoriasis, while IL-22 binding protein (IL-22BP) binds IL-22 to suppress IL-22 signaling." (PMID 32632545, 2020). "IL-1β, together with IL-23, is involved in Th17 differentiation and the production of IL-17 and IL-22, which are crucial in the pathogenesis of psoriasis." (PMID 33149756, 2020). "IL-17, IL-23, and IL-22 cytokines have been closely correlated with IL-36 in human and Aldara-induced psoriasis." (PMID 32345660, 2020). "In psoriasis, even during remission, they become a source of important inflammatory cytokines IL-17A and IL-22." (PMID 31963581, 2020). "Andrographis nallamalayana, which has been introduced as a potent phytomedicine against psoriasis, reduced the level of IL-22 by less than 70% compared with the IMQ-treated control." (PMID 33253155, 2020). "Elevated level of IL-22 in plasma has also been related with psoriasis, which markedly reduced after anti-psoriatic therapy." (PMID 33042126, 2020). "S100A7 is induced by calcium, vitamin D, retinoic acid, bacterial products, TNF-α, IL-17A and IL-22, and is involved in the pathogenesis of psoriasis via its chemotactic activity for neutrophils and CD4+ T lymphocytes." (PMID 32947991, 2020). "The IL-22—IL-22 subunit (IL-22R1) axis has shown a high potential clinical relevance in inflammatory diseases like psoriasis, ulcerative colitis, liver and pancreatic damage, graft-versus-host disease, certain infections, and tumors." (PMID 33042126, 2020). "The transcriptomic signature in keratinocytes within psoriasis plaques is dominated by the IL‐22 and IL‐17 signalling pathways." (PMID 32757303, 2020). "In a psoriasis mouse model, curcumin significantly inhibited secretion of inflammatory factors including interleukin (IL)-17, IL-22, IFN-γ, IL-2, IL-8 and TNF-α in T cells by 30%–60% in vitro." (PMID 32143311, 2020). "Lastly, medically targeted cytokines known to drive inflammatory skin diseases such as psoriasis (IL-17, IL-22, and IL-23) and atopic dermatitis (IL-4, IL-5, IL-13) were not identified in healthy skin." (PMID 33154365, 2020). "Meanwhile, the expression of inflammatory factors (IL-1β, IL-6, TNF-α, IL-17, and IL-22) in serum and kidney tissue of psoriasis-like mice was significantly increased." (PMID 32090080, 2020). "Recently, studies have found IL-17 and IL-22 producing NK cells in both humans and mice, which indicates the potential for NK cell participation in the development of psoriasis." (PMID 32153574, 2020). "In patients with psoriasis, IL-22 levels were found to be elevated in serum and skin lesions and positively correlated with disease severity." (PMID 33182442, 2020). "IL‐22 was similar in T cells of psoriasiform lesions and classical psoriasis, whereas it was substantially reduced in PBMCs." (PMID 31577850, 2020). "IL-22 is predominantly produced by mast cells in patients with psoriasis 73, whereas the IL-17/IL-23 axis in dendritic and T-cells has been previously shown to be crucial for the development, progression and treatment of psoriasis 4,74." (PMID 33204332, 2020). "IL-22 affects the outcome of several diseases, such as multiple sclerosis, psoriasis, inflammatory bowel disease (IBD), Guillain-Barré syndrome (GBS), and West Nile encephalitis." (PMID 32148440, 2020).
psoriasis (continued). "In the present study, KRT6, IL‐17 and IL‐22 protein within psoriasis lesions was decreased, while KRT10 and Tp63 protein in psoriasis lesions was increased by ozone treatment in both patient and IMQ mice psoriatic tissues." (PMID 32168425, 2020). "To accurately illustrate the correlation between IL-22/IL-22R1 and the severity of the psoriasis lesions, we further compared their expression." (PMID 32632545, 2020). "IL-22 expression is upregulated in the skin lesions and serum of patients with psoriasis, and it is strongly related to the disease severity." (PMID 33149756, 2020). "Here we found that the concentration of IL-22 in serum was significantly higher in psoriasis patients than that in healthy controls (HC) (191.1 ± 19.24 pg/mL vs. 20.49 ± 1.739 pg/mL, respectively) (P < 0.0001), consistent with other reports." (PMID 32632545, 2020). "Increased IL-22/IL-22BP ratio of mRNA in psoriasis and stronger staining in epidermis further supported that the IL-22/IL-22R1 axis mainly acted on keratinocytes of psoriasis." (PMID 32632545, 2020). "IL-6 is required for IL-22-mediated skin inflammation and epidermal hyperplasia in psoriasis by regulating the expression of IL-22 receptor chain IL-22R1." (PMID 33149756, 2020). "To evaluate the correlation of IL-22/IL-22R1 and clinical parameters of psoriasis patients, we analyzed the mRNA and protein levels of IL-22/IL-22R1 and psoriasis severity index (PSI) by Pearson correlation analysis." (PMID 32632545, 2020). "In conclusion, IL-22 is a key regulator of proliferation and anti-apoptosis in psoriasis through mediating the Bcl-2 family in keratinocytes and interacting with TNF-α and IFN-γ." (PMID 32632545, 2020). "Our results reveal an anti-apoptotic effect of elevated IL-22 in psoriasis on keratinocytes by regulating Bcl-xL/Bax." (PMID 32632545, 2020). "Lastly, ILC3s are one of the subtypes of immune cells in the skin capable of producing IL-17A and IL-22 and are therefore of specific interest when discussing psoriasis." (PMID 32153574, 2020). "IL-22 is upregulated in patients with psoriatic lesions and previous studies in imiquimod-induced psoriasis mouse models have reported reduced skin lesions in IL-22-deficient mice, indicating the importance of this cytokine in immune-related skin diseases." (PMID 33003458, 2020). "Conforming to what is understood about the workings of the IL-22/IL-22BP axis, it has been further demonstrated that IL-22BP acts in a protective manner in skin-related conditions, as reported in mouse models of psoriasis and atopic dermatitis." (PMID 33003458, 2020). "The chemokine receptor CCR6 is a marker for T cells secreting IL-17 and IL-22, which are the key cytokines in psoriasis pathogenesis." (PMID 32139717, 2020). "On the other hand, epidermal IL-22-producing γδ T cells increase in IL-23-induced psoriasis-like dermatitis." (PMID 32917058, 2020). "Of note, CD1a‐reactive T cells capable of producing IL‐17 and IL‐22 were identified in the blood and skin 69 of psoriasis patients, indicating a potential role for lipid antigens in psoriasis." (PMID 32757303, 2020). "Accordingly, it was shown that if IL-22 was neutralized by antibodies, the development of psoriasis was prevented in the mouse model." (PMID 32392785, 2020). "Taken together, our results demonstrate that IL-36R signaling in keratinocytes plays a major role in the induction of Aldara-induced psoriasis-like dermatitis by triggering early production of IL-23/IL-17/IL-22 cytokines and neutrophil infiltration." (PMID 32345660, 2020). "Serum IL-17A, IL-22, and IL-6 concentrations were significantly higher in psoriasis patients compared with the control group." (PMID 33171607, 2020). "Compared with healthy controls, the skin of patients with psoriasis has been shown to contain increased levels of Th17 cells with IL-17A, IL-17F, and IL-22 proteins being abundantly produced." (PMID 32392785, 2020).
psoriasis (continued). "In contrast to classical psoriasis, psoriasiform lesions showed an increased number of infiltrating IL‐22+ leukocytes." (PMID 31577850, 2020). "IL-22-induces miRNA-122-5p which promotes keratinocyte proliferation by decreasing the expression of Spry2 in the pathogenesis of psoriasis." (PMID 33231565, 2020). "IL-22 levels were increased in serum and lesions from psoriasis patients consistent with previous reports." (PMID 32632545, 2020). "The combination therapy attenuates IMQ-induced psoriasis-like inflammation by downregulating the levels of IL-17A, IL-22, IL-23, and TNF-α in the serum and skin and upregulating Treg cells compared with Acar alone or low-dose CsA alone." (PMID 32316255, 2020). "We established a cell model of psoriasis by stimulating KCs with IL‐22 and then treated the KCs with the ozone therapy." (PMID 32168425, 2020). "The skin lesions showed an increased expression of psoriasis-associated genes such as IL17A, IL22 and DEFB4A." (PMID 32316273, 2020). "In experimental asthma, lipoxins regulate NK or ILC2 activation, and in experimental psoriasis model induced by imiquimod, they reduce IL-17A and IL-22 production via HMGB1 modulation." (PMID 32161582, 2020). "In human skin disorders like allergic contact dermatitis, psoriasis and atopic dermatitis varying amounts of Th17 and IL-22 producing cells were found, indicating disease-specific participation." (PMID 30893757, 2019). "Statistical analysis revealed that patients with psoriasis presented significantly higher concentrations of IL-22 than healthy individuals (p = 0.0000001)." (PMID 30291393, 2019). "The IMQ-induced psoriasis-like skin condition in mice is mediated by several crucial cytokines, of which IL-17A and IL-22 are known to activate PI3K/Akt signaling in epidermal keratinocytes to induce abnormal cell proliferation." (PMID 31252620, 2019). "IL-22 cytokine, an IL-10 family member up regulated in skin disorders such as psoriasis and atopic dermatitis, was used to stress keratinocytes." (PMID 30858525, 2019). "Nevertheless, continuous exacerbated or uncontrolled IL-22 signaling leads to undesirable tissue inflammation, accelerating certain immune pathologies such as psoriasis, atopic dermatitis and rheumatoid arthritis." (PMID 30858525, 2019). "In psoriasis, the expression of IL-22 is increased and its effects are mostly directed towards regulating keratinocyte functions." (PMID 30744173, 2019). "Dual-secreting Th17 T cells presumably are the predominant sources of the psoriasis phenotype-driving cytokines, IL-17A and IL-22." (PMID 31019502, 2019). "Th17 cells can secrete other pro-inflammatory cytokines, such as IL-22, to promote the development of psoriasis." (PMID 31440249, 2019). "With respect to other cytokines and chemokines involved in psoriasis pathophysiology, IL22 is located peripherally at a relatively great distance away on the 2D plot of the psoriasis transcriptome." (PMID 31019502, 2019). "We also used this strategy to correlate the expression of IL17A, IL22, and IL23A with genes linked to psoriasis susceptibility identified through genome-wide association studies (GWAS)." (PMID 31019502, 2019). "Here, we employed recombinant human (rh) IL-22-activated keratinocytes in vitro to investigate the mechanistic role of fisetin in psoriasis-like changes driven by epidermal keratinocytes hyperproliferation." (PMID 31540162, 2019). "Apart from its function in antibacterial defense, IL-22 is the main mediator of the impaired keratinocyte cornification process in psoriasis." (PMID 31028434, 2019). "Since IL-22 has a well-established role in the pathogenesis of psoriasis, this interleukin is a potential target for psoriasis treatments." (PMID 30744173, 2019). "IL-22 is found in the dermal infiltrate of psoriasis plaques, as well as in the blood of patients with psoriasis." (PMID 31275060, 2019).
psoriasis (continued). "In psoriasis, a combination of the inflammatory cytokines IL-17, TNFα, IL-22, and IFNγ drives keratinocyte hyperproliferation and cytokine and chemokine release." (PMID 31673756, 2019). "The combined JAK1/TYK2 inhibitor, SAR-20347, demonstrated in vitro and in vivo concentration-dependent reduction of IL-12, IL-22, and IFNγ-mediated inflammation and tissue pathology in the imiquimod-induced psoriasis model." (PMID 31649667, 2019). "These exciting observations open new tracks to pursue non-toxic natural agents endowed with pro-differentiation properties that can be used as a treatment for skin disorders such as psoriasis as well as uncontrolled IL-22 effects." (PMID 30858525, 2019). "Best known are human dermal mastocytes that recently emerged as a predominant source of IL-22 in atopic dermatitis and psoriasis." (PMID 30291393, 2019). "Patients with psoriasis presented significantly higher concentrations of IL-22 than healthy individuals (p = 0.0000001)." (PMID 30291393, 2019). "Because IL-22 has a detrimental role in psoriasis, the IL-22 level in small intestines was significantly inhibited in rhIL-23R-CHR/Fc and CsA-treated mice compared to that in the model group according to immunofluorescence analysis of the small intestine." (PMID 31454926, 2019). "Correlation (R-values) of IL17A, IL22, and IL23A with genes linked to psoriasis susceptibility through genome-wide association studies." (PMID 31019502, 2019). "While IL-17/IL-22-producing T cells are mainly found in the initial phases of psoriasis, IFN-γ-producing Th1 and Tc1 cells accumulate during the chronic phase of the disease." (PMID 31284527, 2019). "More importantly, we have found that PBMCs from patients with psoriasis stimulated with SEB secreted significantly higher concentrations of IL-22 than those stimulated with IL-12, or PMA." (PMID 30291393, 2019). "For instance, high serum levels of this cytokine have been shown to correlate with poor disease prognosis in psoriasis, and psoriatic skin has also been shown to express higher levels of IL-22 mRNA relative to normal skin from controls." (PMID 31781680, 2019). "Twenty-four hours after the eighth application of IMQ on day 7, the mRNA expression of TNF-α, IL-12/IL-23, IL-17, and IL-22 increased in psoriasis-like dermatitis as compared with that in control mouse skin." (PMID 30838224, 2019). "Correlation (R-values) of IL17A, IL22 and IL23A in psoriasis with genes linked to atopic dermatitis susceptibility through genome-wide association studies." (PMID 31019502, 2019). "Previous studies have reported that the pathogenesis of psoriasis is related to the IL-23/IL-17/IL-22 axis." (PMID 31736959, 2019). "Another possibility is that other cell types, such as γδ T cells or mast cells, contribute to the IL-22 production in psoriasis." (PMID 31019502, 2019). "It has been shown that Th17 cells and related cytokines (IL-23/IL-17/IL-22 axis) participated in the pathogenesis of psoriasis." (PMID 31736959, 2019). "In case of inflammatory skin disorders, a coexpression-model for IFN-γ, IL-4, IL-17, and IL-22 with specific pattern for psoriasis, atopic eczema and allergic contact dermatitis was proposed." (PMID 30893757, 2019). "We examined a relation between the plasma concentration of IL-22 and the severity of psoriasis (PASI score)." (PMID 30291393, 2019). "IL-17A and IL-22 have similar pathological effects in inflammatory diseases, such as psoriasis and arthritis." (PMID 29401501, 2018). "In chronic inflammatory skin diseases like psoriasis, the proliferation of keratinocytes can be induced by cytokines like IL-22 and interleukin-2042." (PMID 29752469, 2018). "IL-17, in cooperation with other cytokines such as TNFα and IL-22, induces the development of the psoriasis phenotype through tissue cell activation." (PMID 29316717, 2018).